NSRP1 (nuclear speckle splicing regulatory protein 1)
Description:
RNA-binding protein that mediates pre-mRNA alternative splicing regulation. Through CCDC118 regulation, may promote pre-adipocyte differentiation (By similarity).
Synonyms: NSrp70; CCDC55; DKFZP434K1421; HSPC095; NEDSSBA
Tractability: PROTAC: UniProt records ubiquitination sites on it; ubiquitination databases record sites on it; its protein half-life has been measured.
Gene: Protein-coding gene on chromosome 17 (30,115,521 to 30,186,475, forward strand). Ensembl gene ENSG00000126653.
Subcellular location: Nucleus; Nucleus speckle
Subcellular location (Human Protein Atlas): Nucleoplasm
Pathways (Reactome):
Metabolism of RNA: mRNA Splicing - Major Pathway
Gene Ontology:
Molecular function: mRNA binding; protein binding; RNA binding
Biological process: developmental process; regulation of alternative mRNA splicing, via spliceosome; positive regulation of adipose tissue development
Cellular component: nuclear speck; nucleoplasm; nucleus; ribonucleoprotein complex
Genetic constraint (gnomAD): Loss-of-function variants: 18 observed, 45.85 expected, observed/expected ratio (o/e) 0.39, 90% interval 0.27 to 0.58. The upper end of that interval is the gene's LOEUF score, 0.58, which puts it in group 2 of 6, group 1 being the genes least tolerant of losing a copy. Missense variants: 516 observed, 576.51 expected, observed/expected ratio (o/e) 0.9, 90% interval 0.83 to 0.96. Synonymous variants: 185 observed, 191.74 expected, observed/expected ratio (o/e) 0.96, 90% interval 0.86 to 1.09.
Gene-disease validity (ClinGen):
ClinGen rates the evidence that NSRP1 causes each of these diseases.
neurodevelopmental disorder with spasticity, seizures, and brain abnormalities (autosomal recessive): Moderate.
Homologues: Orthologues: chimpanzee NSRP1 (99% identical), macaque NSRP1 (92% identical), dog NSRP1 (84% identical), rabbit NSRP1 (82% identical), guinea pig NSRP1 (81% identical), pig NSRP1 (75% identical), mouse Nsrp1 (73% identical), rat Nsrp1 (72% identical), tropical clawed frog nsrp1 (45% identical), zebrafish nsrp1 (38% identical), Caenorhabditis elegans ccdc-55 (22% identical), Drosophila melanogaster CG15747 (20% identical). Paralogues in human: EFCAB5 (16% identical).
Diseases named in the same sentence as NSRP1 in open-access papers:
NSRP1 is named in the same sentence as 11 diseases in open-access papers, as found by Europe PMC text mining. Sharing a sentence is not in itself a finding about the gene and the disease. The quoted sentences say what the papers report.
breast carcinoma (2 papers, 2021 to 2025). "In the current study, we identified NSRP1 as a downregulated RBP in CDK4/6i resistant breast cancer whose high expression was associated with good prognosis of patients with ER+ breast cancer." (PMID 39667501, 2025). "According to the clinical and expression data, 2 downregulated RBPs (PDCD4 and NSRP1) were significantly associated with prolonged overall survival of the patients with LumA and LumB breast cancer." (PMID 39667501, 2025). "Therefore, the data collectively discovered an NSRP1/NSD2/IFN axis implicated in CDK4/6i resistance in ER+ breast cancer cells." (PMID 39667501, 2025). "Nonetheless, the current study is limited to providing direct evidence for the function of NSRP1 in immune suppression, which cannot be concluded that NSRP1 exerts its function via regulating immune cell infiltration directly in breast cancer cells." (PMID 39667501, 2025). "The study unveiled a critical role of NSRP1 downregulation in CDK4/6i resistance development, suggesting NSRP1 as a promising biomarker for patients with ER+ breast cancer." (PMID 39667501, 2025). "In breast cancer cells, silencing NSRP1 reduced sensitivity toward palbociclib while the overexpression of NSRP1 sensitized cells to palbociclib." (PMID 39667501, 2025). "The findings manifested a tumor suppressor function of NSRP1 in ER+ breast cancer cells, providing novel insights in addition to the reported anti-metastasis function of NSRP1 in triple-negative breast cancer cells." (PMID 39667501, 2025). "NSRP1 also regulates numerous alternative splicing (AS) events in breast cancer cells, several of which are key regulators of the IFN signaling pathway." (PMID 39667501, 2025). "Our data also showed that NSRP1 downregulation conferred palbociclib resistance in ER + breast cancer cells and strongly alleviated cell cycle arrest in the G0/G1 phase upon palbociclib treatment." (PMID 39667501, 2025). "The data collectively showed that NSRP1 negatively regulated CDK4/6i resistance in breast cancer cells." (PMID 39667501, 2025). "The data also identified AS events and the IFN pathway regulated by NSRP1 in breast cancer cells, providing novel insights into understanding the development of CDK4/6i resistance and optimizing treatment strategies for patients." (PMID 39667501, 2025). "Mechanistically, RNA-Seq revealed that the downregulation of NSRP1 strongly activated the IFN pathway in breast cancer cells via regulating exon skipping of several regulators of the IFN signaling." (PMID 39667501, 2025). "Interestingly, our current study showed that NSRP1 downregulation not only inhibited cell proliferation of ER+ breast cancer cells but also conferred CDK4/6i resistance." (PMID 39667501, 2025). "Our data showed that silencing of NSD2 also decreased the expression of the IFN-stimulated genes in ER + breast cancer cells, suggesting NSRP1-regulated AS of NSD2 might contribute to the activity of the IFN pathway." (PMID 39667501, 2025). "Here, via RNA-Seq data analysis, we found NSRP1 regulated the splicing of pre-mRNAs transcribed from many oncogenes involved in metabolic pathways, endocrine resistance, and pathways in cancer in ER+ breast cancer cells." (PMID 39667501, 2025). "Most recently, it has been revealed that the expression of NSRP1 was decreased in subtypes of breast cancer and was associated with no recurrence and no metastasis status." (PMID 39667501, 2025). "Here, we report that NSRP1, a regulator of alternative mRNA splicing is downregulated in CDK4/6i resistant breast cancer cells and contributes to CDK4/6i resistance by mediating alternative splicing of NSD2 mRNA and activation of the IFN signaling pathway." (PMID 39667501, 2025). "In two established CDK4/6i resistant breast cancer cell lines (MCF7-PalR and MCF7-AbeR), we observed downregulation of NSRP1 protein expression compared with the parental MCF7 cells." (PMID 39667501, 2025).
breast carcinoma (continued). "The results manifested that NSRP1 might be involved in the immunosuppressive microenvironment and this could partly explain the NSRP1-related CDK4/6i resistance in breast cancer cells." (PMID 39667501, 2025).
breast tumors (1 paper, 2025). "Collectively, these data manifested that ER+/Her2-breast tumors with low NSRP1 expression were potentially associated with an immunosuppressive tumor microenvironment, which might contribute to immune escape and poor prognosis." (PMID 39667501, 2025).
Hypertension (1 paper, 2013). The presence of chronic increased pressure in the systemic arterial system. "Among the down-regulated DEGs in the MCA of the hypertension only group were FOXN1, NSRP1 and THUMPD3." (PMID 23874591, 2013).
triple-negative breast carcinoma (1 paper, 2025). An invasive breast carcinoma which is negative for expression of estrogen receptor (ER), progesterone receptor (PR), and human epidermal growth factor receptor 2 (HER2). "Recent studies have revealed the vital roles of NSRP1 in the immune system development and suppressing metastasis of triple-negative breast cancer." (PMID 39667501, 2025).
cancer (2 papers, 2021 to 2025). A tumor composed of atypical neoplastic, often pleomorphic cells that invade other tissues. "KEGG enrichment analysis showed that the genes with altered SE events upon NSRP1 silencing were involved in cancer-related processes, such as Metabolic Pathways, Endocrine Resistance, and Pathways in Cancer." (PMID 39667501, 2025). "Therefore, a systematic study is needed to explore the function of NSRP1 in cancer immunology." (PMID 39667501, 2025).
tumor (2 papers, 2021 to 2025). "It was found that NSRP1 was lowly expressed in Immune score low/Stromal score high tumors compared with Immune score high/Stromal score low tumors, suggesting NSRP1 was associated with an immunosuppressive tumor microenvironment." (PMID 39667501, 2025). "Because the infiltration of immune and stromal cells represents the tumor microenvironment in tumor tissues, we explored the association between the expression of NSRP1 and ESTIMATE scores (ESTIMATE Immune score and ESTIMATE Stromal score) in TCGA ER+/HER2- tumors." (PMID 39667501, 2025).
neurodevelopmental disorder (1 paper, 2025). A behavioral and cognitive disorder with onset during the developmental period that involves impaired or aberrant development of intellectual, motor, or social functions. "Homozygous loss-of-function alleles of NSRP1 lead to a severe neurodevelopmental disorder, while NSRP1 function has been linked to adipogenesis and modulation of weight in pigs." (PMID 40971676, 2025).
NSRP1 also shares sentences with these, for which no sentence is quoted: B cell lymphopenia (1 paper); genetic disorders (1); lymphopenia (1); melanoma (1).